NF2 (NF2, moesin-ezrin-radixin like (MERLIN) tumor suppressor)
Diseases named in the same sentence as NF2 in open-access papers (continued):
Sharing a sentence is not in itself a finding about the gene and the disease.
liver cancer (7 papers, 2014 to 2025). An epithelial or non-epithelial malignant neoplasm that arises from the liver. "Another study investigated the effect of NF2 mutations on primary liver cancers in human liver tissue." (PMID 39796693, 2024). "Deactivating NF2 mutations have been identified in human liver cancers, including 1.9% of HCCs and 5.3% of iCCAs." (PMID 37174657, 2023). "Our data not only track the levels of Merlin in HCC but also provide new evidence that an Nf2 splicing variant in liver cancer is responsible for tumour proliferation and metastasis." (PMID 26443326, 2015). "The implications of NF2/Merlin loss in liver cancer models have also been explored." (PMID 39796693, 2024). "Twenty-three percent of liver cancers have mutations in NF2." (PMID 24393766, 2014). "The loss‐of‐function of NF2 severely compromises Hippo signaling activity through the major effector YAP, resulting in hepatomegaly and liver cancers." (PMID 33818013, 2021). "Moreover, knockout of NF2, DYRK1A, and SOX9 in another TSPAN8-expressing human liver cancer cell line, SNU878, similarly resulted in a downregulation of TSPAN8." (PMID 40801599, 2025).
spinal cord ependymoma (6 papers, 2007 to 2024). An ependymoma that arises from the spinal cord. "NF2 somatic mutations are the most frequent individual gene mutations in spinal cord ependymomas, where they reach 43%." (PMID 25775275, 2015). "Similarly, MYC-amplified spinal cord ependymoma has consistently been shown to have inactivating mutations and loss of heterozygosity of the NF2 gene, which correlates with unfavorable outcomes." (PMID 38254893, 2024). "Bevacizumab has shown some efficacy in spinal cord ependymomas occurring in NF2 patients, especially when these tumors harbor an important cystic component, and can also result in some response in recurrent spinal cord ependymomas." (PMID 34885237, 2021). "In contrast to their counterparts arising in the brain, spinal cord ependymomas (SP-EPN) show frequent inactivating mutations and/or loss of heterozygosity of the NF2 gene." (PMID 32641156, 2020). "Since most spinal cord ependymomas in NF2 patients do not cause any symptoms even for prolonged periods of time, tumor resection should be reserved for patients developing neurological symptoms or tumor progression." (PMID 39713042, 2024). "We report a novel group of clinically aggressive spinal cord ependymomas characterized by Grade III histology, MYCN amplification, an absence of NF2 alterations or other recurrent pathogenic mutations, and a unique methylation classifier profile." (PMID 32641156, 2020).
astrocytoma (5 papers, 2019 to 2022). "Moreover, the single NF2 disease‐associated variant identified in exon 17 was observed in a somatic astrocytoma sample from one individual." (PMID 35332608, 2022).
depression (5 papers, 2014 to 2024). "Interestingly, besides the disease severity, depression symptoms showed the strongest association with quality of life in NF2-SWN." (PMID 38521834, 2024). "Individuals with NF1 and NF2 have low quality of life, and this correlates with pain, anxiety, and depression, which are prevalent in NF1 and NF2." (PMID 32642740, 2020). "Our findings highlight the importance of multidisciplinary management of individuals with NF1 and NF2, and we suggest screening for pain and depression in routine assessments of individuals with NF." (PMID 32642740, 2020). "One might expect that anxiety and depression would be a major feature of NF2, and this is the case for some." (PMID 24619350, 2014). "When analyzing the EQ-5D-5L, we found that a high proportion of patients reported some degree of pain/discomfort (66% for NF1 and 73% NF2, respectively) and anxiety/depression (61% and 68% for NF1 and NF2, respectively)." (PMID 32642740, 2020).
gastric cancer (5 papers, 2011 to 2023). A primary or metastatic malignant neoplasm involving the stomach. "Recent studies comparing gastric cancer and normal tissue have identified a number of genetic markers, including diagnostic markers [NF2, INHBA, SFRP4], prognostic markers [CD9, CDH17, PDCD6], and gastric cancer-associated genes [MUC13, CLDN1, Ki67 and CD34]." (PMID 22133303, 2011).
Gorlin syndrome (5 papers, 2019 to 2025). "Additionally, five patients had mutations detected in the tumor suggesting a cancer predisposition syndrome (Von Hippel Lindau syndrome, Gorlin syndrome, NF1 and NF2, and CMMRD), which were then confirmed in the germline." (PMID 31827999, 2019). "Familial MM can be associated with genetic syndromes such as Neurofibromatosis type 2 (NF-2), Cowden syndrome, Multiple Endocrine Neoplasia 1 (MEN1), Werner syndrome, Rubinstein–Taybi syndrome, Gorlin syndrome, and Li–Fraumeni syndrome." (PMID 40283561, 2025).
Hypertension (5 papers, 2018 to 2025). The presence of chronic increased pressure in the systemic arterial system. "The etiology remains elusive, but potential triggers include genetic predisposition, smoking, obesity, hypertension, and immunocompromised status, which may be associated with alterations in the NF2 and CDKN2A genes." (PMID 39850820, 2024).
intraventricular meningioma (5 papers, 2019 to 2024). A meningioma that affects the ventricles of the brain. "NF2 mutations are the most common genetic alterations found in intraventricular meningiomas." (PMID 39768979, 2024). "Intraventricular meningiomas, on the other hand, certainly harbored NF2 mutations without the other common variants." (PMID 35774130, 2022).
lung adenocarcinoma (5 papers, 2010 to 2023). A carcinoma that arises from the lung and is characterized by the presence of malignant glandular epithelial cells. "The genes whose loss is predicted to be detrimental to EGFR-driven tumors (i.e., Keap1, Lkb1, and Nf2) are rarely co-mutated with EGFR in human lung adenocarcinoma as predicted." (PMID 37828026, 2023). "NF2 mutation contributes to drug resistance in multiple cancer types, while molecular alterations of NF2 is found in 5% of lung adenocarcinoma patients and 15% of lung squamous cell carcinoma patients." (PMID 37569866, 2023). "NF2 mutations, albeit rare, were reported in lung adenocarcinoma, as well." (PMID 27229317, 2016). "Tumor suppressor in lung cancer-1 (TSLC1) belongs to immunoglobulin superfamily of cell adhesion molecule and differentially expressed in adenocarcinoma of the lung (4.1B)belongs to NF2/ERM/4.1 protein superfamily." (PMID 21081044, 2010). "Absent NF2 expression was noted in one lung adenocarcinoma case, and two papillary thyroid carcinoma cases." (PMID 27229317, 2016).
metastatic tumors (5 papers, 2014 to 2026). "Therefore, we speculate that these differentiated cancer cells in metastatic tumors exhibit low YAP and Wnt activity and may be less reliant on YAP and Wnt signaling regulated by the loss of NF2 and RASA1, compared to CSCs." (PMID 37730636, 2023). "Two metastatic tumors (Cases 22 and 23) harbored heterozygous SMARCB1 deletions accompanied by broad 22q losses affecting CHEK2, NF2, and EP300." (PMID 41317331, 2026).
ovarian carcinoma (5 papers, 1994 to 2024). A malignant neoplasm originating from the surface ovarian epithelium. "The germline mutation of NF2 in ovarian cancer has rarely been studied, and the relationship between germline mutations in NF2 and familial inheritance of ovarian cancer requires further investigation." (PMID 38817903, 2024). "Previous studies have focused on somatic mutations in NF2 and found that these mutations are highly prevalent mainly in brain tissue, with a frequency of only 1% in the ovarian cancer population." (PMID 38817903, 2024). "Conversely, a germline NF2 variant, enriched in ovarian cancer, was depleted in the BC." (PMID 32295625, 2020). "​Ovarian cancer had the characteristics of high familial incidence, and the results of our cohort showed that XPA and NF2 were associated with familial inheritance of ovarian cancer." (PMID 38817903, 2024). "Another study revealed that the frequency of NF2 detection in the ovarian cancer population was 2.56%, which is close to the germline carrier frequency in the current cohort (2.31%)." (PMID 38817903, 2024). "Analysis of 9 of the 17 exons of NF2 by single-strand conformational polymorphism (SSCP) in 67 ovarian carcinomas did not detect any somatic mutations, suggesting that NF2 is not involved in the pathogenesis of ovarian carcinoma." (PMID 7947096, 1994).
pancreatic cancer (5 papers, 2015 to 2026). "Thus, NF2 status dictates the adaptability of pancreatic tumors under nutrient limitation, with NF2 inactivation endowing PDACs with the ability to survive the constraints of the harsh tumor microenvironment." (PMID 41480769, 2026). "As well as this, decreased expression of NF2 and LKB1 genes in pancreatic tumor and cancer cell lines also contribute to evading growth suppression." (PMID 28587243, 2017).
Peripheral schwannoma (5 papers, 2020 to 2025). The presence of a peripheral schwannoma. "In the category comparison of NF2-associated peripheral schwannomas, lesions located at the trunk exhibited good functional and pain outcomes compared to tumors at the head/brachial plexus and neck." (PMID 35771312, 2022). "The detection of a peripheral schwannoma at a very unusual location and a very young age in our patient prompted, justifiably, further investigation, based on which the Manchester diagnostic criteria were fulfilled, thus establishing the diagnosis of NF2." (PMID 39618887, 2024). "Peripheral schwannomas showed significant better pre- and postoperative motor (p < 0.001, p = 0.011), and preoperative sensory function (p = 0.032) and less pain after surgery (p = 0.032) compared to intraspinal NF2-associated tumors." (PMID 35771312, 2022).
skull base tumors (5 papers, 2017 to 2025). "Mutations in NF2 were identified in 4/10 patients, of these 94% were non-skull base tumours." (PMID 36882706, 2023). "Genotype (p = 0.004) and WHO grade (p = 0.002) were significantly associated with tumor location: NF2 alterations predominated in convexity and spine, while TRAKLS mutations (TRAF7, AKT1, KLF4, SMO) were enriched in lower-grade skull base tumors." (PMID 40951339, 2025). "NF2 alterations predominated in cerebral convexity (29/58; 50%) and spinal tumors (5/7; 71%), while TRAKLS mutations were enriched in skull base tumors (15/22; 68%)." (PMID 40951339, 2025).
childhood cancer (4 papers, 2017 to 2026). "As CNS tumors are the leading cause of pediatric cancer related death, managing these tumors in NF1 and NF2-SWN patients requires coordinated multidisciplinary life-long care." (PMID 41847710, 2026).
cholangiocarcinoma (4 papers, 2022 to 2024). A carcinoma that arises from the intrahepatic biliary tree (intrahepatic cholangiocarcinoma) or from the junction, or adjacent to the junction, of the right and left hepatic ducts (hilar cholangiocarcinoma). "The physiological importance of this dual mechanism is supported by our findings that loss of Vgll4 dramatically enhanced intrahepatic cholangiocarcinoma formation in Nf2-deficient livers." (PMID 36522128, 2022). "In summary, the current study provides novel evidence that KAT2B plays an important tumor suppressive role in cholangiocarcinoma through interaction with SP1 to enhance the expression of NF2 which leads to subsequent inhibition of oncogenic YAP." (PMID 38641672, 2024). "We found that loss of Vgll4 completely rescued the developmental defects of Yap mutant livers and lungs, greatly enhanced Nf2 mutant liver intrahepatic cholangiocarcinoma development, and ameliorated CCl4-induced liver injury." (PMID 36522128, 2022). "In NF2 knockout models, the proliferation of cells in bile duct areas and overgrowth of the liver were frequently observed, and these mice eventually developed HCC and cholangiocarcinoma (CCA)." (PMID 35453784, 2022).
Chordoid Meningioma (4 papers, 2018 to 2024). A WHO grade II, usually recurring meningioma characterized by the predominance of tissues that are histologically similar to chordoma. "Taken together, it appears that NF2 mutation and chromosome instability can account for majority of recurrences in chordoid meningioma." (PMID 35440040, 2022). "Interestingly, the transitional meningioma (M1) had a second hit of NF2 and the chordoid meningioma (M2) had a CREBBP mutation." (PMID 39066986, 2024). "NF2 mutations in chordoid meningioma strongly and significantly lowered patient RFS." (PMID 31963394, 2020). "Genetically, previous studies found that chordoid meningiomas had sparce NF2, TRAF7, KLF4, SMO, AKT1 and SMARCB1 mutations common to non-chordoid meningioma." (PMID 35440040, 2022). "NF2 was usually highly expressed in the cytoplasm of neoplastic cells in both secretory and chordoid meningioma." (PMID 29983887, 2018). "Chordoid meningiomas were enriched in mutations in chromatin remodeling genes EP400 (8/11,73%) KMT2C (4/11, 36%) and KMT2D (4/11, 36%), and showed low or absent NF2, TERT, SMO, and AKT1 mutations." (PMID 35440040, 2022). "One case of multiply recurrent chordoid meningioma from a patient who succumbed to disease completely lacked NF2 expression." (PMID 29983887, 2018).
collecting duct carcinoma (4 papers, 2020 to 2024). "In the rare RCC category, collecting duct carcinoma (CDC) harbors mutations in NF2, SETD2, SMARCB1, FH, and CDKN2A genes while renal medullary carcinoma is distinctively characterized by loss of SMARCB1/INI1 tumor suppressor protein." (PMID 32575429, 2020). "Alterations in SETD2, NF2, ARID1, and MLH1 were identified in collecting duct carcinoma samples, although none were significantly associated with gene signatures." (PMID 38652565, 2024).
deafness (4 papers, 2018 to 2022). An inherited or acquired condition characterized by the complete loss of the ability to hear from one or both ears. "Ordinarily, the natural course of hearing loss in NF2 patients is progressive deafness." (PMID 31848332, 2019). "Most NF2 patients eventually present deafness in their lifetime, and most treatment modalities are rarely effective to revert the natural course of hearing dysfunction." (PMID 36185258, 2022). "NF2 patients showed good hearing function (H1/2) in 10 cases, moderate hearing (H3/4) in 12 cases, and at least functional deafness (H5/6) in 12 cases according to the Hannover Classification." (PMID 29515781, 2018). "The most frequent causative deafness gene was TMC1 (DFNA36) (3 cases), followed by the next tier of genes (2 cases each) (CDH23, COCH, SLC26A4, TMPRSS3, ATP1A3), and the genes that were detected only once (ACTG1, GJB2, ILDR1, MYO7A, MYO15A, NF2, NLRP3 and SERPNB6)." (PMID 32238869, 2020).
Fibrous Meningioma (4 papers, 2021 to 2025). A WHO grade I meningioma characterized by the presence of spindle cells that form bundles in a collagen matrix. "It is well established that fibrous meningiomas commonly harbor NF2 mutations or chromosomal loss, whereas meningothelial tumors frequently carry TRAF7 and AKT1 mutations." (PMID 41154381, 2025). "Among WHO grade I tumors, NF2 mutations or 22q loss were significantly more frequent in fibrous meningioma than in other pathological types (p = 1.3 × 10–7)." (PMID 33772057, 2021). "NF2 aberrations are known to be enriched in transitional and fibrous meningioma in the intracranial skull base and psammomatous meningioma in the spinal cord." (PMID 40815185, 2025).
neuropathy (4 papers, 2014 to 2020). A disorder affecting the nervous system that manifests with pain, tingling, numbness, and/or muscle weakness. "Our group recently deciphered a promising pathomechanism indicating how the loss of merlin could contribute to the development of NF2-related neuropathy in an axon-intrinsic manner." (PMID 25012216, 2014). "Thirdly, as we will discuss later, NF2-related neuropathy may result from the loss of just one allele as a consequence of cell type-specific haploinsufficiency in neuronal cell types." (PMID 25012216, 2014). "Recently, a neuronal function of merlin has been explored in more detail in our laboratory, emphasizing an implication in NF2-related neuropathy as well as in the bi-directional communication of axons and Schwann cells." (PMID 27236462, 2016). "Notably, the expression abnormalities of both Nrg1 type III and ErbB2 receptor appear to be very specific to NF2 disease and much more pronounced than in other axonal types of neuropathies." (PMID 25012216, 2014). "To date, the pathogenesis of NF2-related neuropathy is not completely understood." (PMID 25012216, 2014). "Strikingly, NF2-associated neuropathy often occurs in the absence of nerve damaging tumors, suggesting tumor-independent events." (PMID 25012216, 2014).
ovarian insufficiency (4 papers, 2022 to 2025). "Basonuclin1 is a mutated gene from the Chinese primary ovarian insufficiency lineage, and its deficiency triggers oocyte ferroptosis through the NF2-YAP pathway." (PMID 37589858, 2023).
perineurioma (4 papers, 2022 to 2025). A usually benign perineurioma not associated with a nerve, arising from the soft tissues. "Intraneural perineuriomas harbor missense mutations in TRAF7, whereas soft tissue perineuriomas commonly show deletions of chromosome 22q (NF2) and deletions of chromosome 17q11 (NF1), as well as chromosome 2p deletions or rearrangements or deletions of chromosome 10q (sclerosing variant)." (PMID 37046591, 2023).
rhabdoid tumor (4 papers, 2009 to 2023). An aggressive malignant embryonal neoplasm usually occurring during childhood. "Here the authors present new mouse models and show that early Smarcb1 loss causes rhabdoid tumors whereas loss at later stages combined with Nf2 gene inactivation causes shwannomas." (PMID 28824165, 2017).
Tinnitus (4 papers, 2022 to 2024). Tinnitus is an auditory perception that can be described as the experience of sound, in the ear or in the head, in the absence of external acoustic stimulation. "Up to 75% of patients with the sporadic form and 80% of patients with NF2-associated VS have tinnitus." (PMID 38892775, 2024). "Just as is seen in NF2 associated VS, patients with NF2 may also present with tinnitus as an initial symptom, although it may be less common due to increased surveillance and earlier detection." (PMID 38892775, 2024).
triple-negative breast carcinoma (4 papers, 2020 to 2024). An invasive breast carcinoma which is negative for expression of estrogen receptor (ER), progesterone receptor (PR), and human epidermal growth factor receptor 2 (HER2). "MDA-MB-231 is a triple negative breast cancer cell line that harbors a deletion in the NF2 gene, and therefore, exhibits increased YAP activity." (PMID 36523977, 2022).
café-au-lait macules (3 papers, 2012 to 2025). "Risk factors for internal nerve sheath tumors included decreasing numbers of café-au-lait macules in NF1 patients (P = 0.003) and history of skeletal abnormalities in NF2 patients (P = 0.09)." (PMID 22558206, 2012).
epilepsy (3 papers, 2020 to 2023). A brain disorder characterized by episodes of abnormally increased neuronal discharge resulting in transient episodes of sensory or motor neurological dysfunction, or psychic dysfunction. "Therefore, we provide a new paradigm for the development of therapeutic strategies for epilepsy and neurological diseases associated with deregulation of NF2 and Mdm2." (PMID 33414453, 2021). "However, little is known yet to explain the underlying mechanisms of NF2-S10 dephosphorylation and the role of NF2 phosphorylation in seizure susceptibility and/or epilepsy." (PMID 33414453, 2021).